IL10 (interleukin 10)
Diseases named in the same sentence as IL10 in open-access papers (continued):
Sharing a sentence is not in itself a finding about the gene and the disease.
tumor (continued). "TIGIT ligands on the surface of tumor-infiltrating CD8+T cells or Tregs can bind to PVR receptors of tumor cells or dendritic cells, promote the production of anti-inflammatory cytokines such as IL-10 and inhibit the immune response." (PMID 37035135, 2023). "Skin KS had higher IL-6 and IL-10 gene expression compared to normal tissue, whereas GI KS had higher IL-1A expression." (PMID 37740179, 2023). "MDSCs promote hepatocarcinogenesis in a variety of ways including the recruitment of regulatory T cells via the secretion of IL-10 and TGF-β and inhibition of cytotoxic T cells by stimulating the expression of PD-L1 on tumor cells, thus mediating immune evasion." (PMID 36831649, 2023). "Furthermore, nanoformulations affected the expression of proteins responsible for interactions between the tumor and its immune microenvironment: surface markers (PD-L1, TIM3, CD47) and IL-10." (PMID 36986829, 2023). "An in vivo study showed that ibrutinib monotherapy failed to achieve tumor regression in murine models but decreased B cell infiltration and inhibited activation and IL-10 production." (PMID 37190284, 2023). "First, we validated the clinical relevance of IL-10/IL-10R and CSF1R in tumor samples." (PMID 37586318, 2023). "M2 TAMs secrete a variety of inflammatory factors and chemokines—such as TGF-β, IL-10, VEGF, MMP, CCL15, CCL17, and CCL22—to stimulate angiogenesis, maintain tumor cell stemness, facilitate immune infiltration, remodel tissue, and induce drug resistance, thus promoting M2 polarization." (PMID 37759870, 2023). "Moreover, it is suggested that the combined functions of Treg cells, IL-10, and type I IFN were required for effective suppression of Th17-induced inflammation in the tumor microenvironment." (PMID 37235332, 2023). "Breg cells support carcinogenesis, tumor progression, and a metastatic process suppressing Th1, Th17, and CD8+ cytolytic T-cell responses, through the production of immunosuppressive cytokines (e.g., TGF-β, IL-35, and IL-10)." (PMID 37046842, 2023). "In addition, the combination of IL-10/Fc and PD1/PDL1 blockade showed stronger anti-tumor efficacy, contributing to a durable efficacy in the mouse CT26 colorectal tumor model." (PMID 37398660, 2023). "M2 macrophages are alternatively activated macrophages that secrete large amounts of anti-inflammatory cytokines, such as IL-8, IL-10, and TGF-β, to promote tumor vasculature development, CD8+ T-cell apoptosis, and the Th1 immune response, thus favoring tumor growth and metastasis." (PMID 37275909, 2023). "In addition, observably increased Th1 cytokines (IFN‐γ, IL‐12a and IL‐2) and decreased Th2 cytokines (IL‐6, IL‐10 and TGF‐β) in serums were also detected in tumor‐bearing mice post Pres and irradiation treatments." (PMID 37875395, 2023). "The main reason is that it can produce IL-10, TGF-β, and IL-35 in anti-tumor immunity." (PMID 37024932, 2023). "In our study, IL-10 was elevated in GBM patients, as was observed in several other studies that revealed its inhibitory effect on the antitumor response while promoting the proliferation of tumor cells." (PMID 38003396, 2023). "Our previous studies demonstrated that many suppressive cytokines secreted in the tumor microenvironment impact the motility and immune functions of DCs, such as transforming growth factor-β1 (TGF-β1), interleukin-10 (IL-10), and vascular endothelial growth factor (VEGF)." (PMID 36826287, 2023). "This suppressive action is carried out by TGF-β, IL-10 cytokine, and CCL2 (MCP-1), which are released by the glioma and microenvironmental cells, which recruits Tregs, MDSC, and TAMs infiltrating the tumor disrupting lymphocyte function." (PMID 37165457, 2023). "‐LPMs characterized in tumor‐bearing mice as F4/80high GATA6+ cells that proliferated during tumor progression.‐No expression of prototypical protumoral genes (IL10, TGFB and Retnla), but of proinflammatory genes (IL6, TNFA and IL1B)." (PMID 36658699, 2023).
tumor (continued). "Flow cytometry analysis of peripheral blood and tumor/paraneoplastic tissues from colorectal cancer (CRC) patients and healthy controls revealed the accumulation of LAP + CD4 + T cells in the tumor microenvironment, with immune evasion mediated by IL-10 and TGF-β promoting tumor metastasis." (PMID 37689664, 2023). "Bregs express IL-10, TGF-β, and TNF-α in most inflammatory and tumor microenvironments." (PMID 37432957, 2023). "Multiple proinflammatory/immune recruitment (IL-1β, IL-6, IL-8, TNFα, IFNα, MIP-1β, CXCL12) and immune suppressive cytokines (IL-10) were found to be induced by tumor line-derived sEVs but not those derived from normal pancreatic cell lines." (PMID 37834100, 2023). "In addition, γδT cells account for up to 20% of T cells in the lung ecosystem and may promote tumour growth by inducing neoangiogenesis and evasion by restricting the action of APCs, recruiting MDSCs, and secreting immunosuppressive molecules such as IL-4, IL-10, and TGF-β." (PMID 37189436, 2023). "Exosomes can upregulate the expression of proinflammatory factors and induce the secretion of some proinflammatory chemokines and cytokines, such as IL10, TGF-β2, and IL-35, in the tumor local inflammatory microenvironment, thus weakening antitumor immune responses." (PMID 36979391, 2023). "Moreover, IL10 can also stimulate IL6 expression and synthesis, which can also support tumor progression, and, naturally, already oversecreted by MSCs." (PMID 36661524, 2023). "Additionally, the TME is packed with Tregs, MDSCs, TAMs and TANs and promotes tumor survival through the secretion of TGF-β, IL-10, nitric acid, and IDO (indoleamine 2,3 dioxygenase)." (PMID 37328842, 2023). "It should be noted that CAFs are not considered IL-10-producing cells in the tumor microenvironment." (PMID 38008819, 2023). "Tregs produce immunosuppressive cytokines (IL-10, TGF-β), express coinhibitory molecules (CTLA-4, PD-1, PD-L1), and capture the Th1 cytokine IL-2, thereby inhibiting T cell-mediated responses and promoting immune escape of the tumor." (PMID 38136307, 2023). "Tumor associated macrophages (TAMs) which are broadly considered M2-like secrete a large number of cytokines including PGE2, epithelial growth factor (EGF), epithelial growth ligands of the factor receptor (EGFR), IL-10 and TGF-β, which stimulate tumor cell proliferation and survival." (PMID 37064113, 2023). "Approximately 20% of the infiltrating γδT cells in human advanced breast cancer samples express CD73, and these cells may play an immunosuppressive role by producing immunosuppressive molecules such as IL-10, IL-8 and ADO, thus promoting tumor growth." (PMID 36793048, 2023). "The results revealed that SNHG17 was highly expressed in tumor tissues and positively correlated with the level of TAM markers CD163, CD206, and IL-10, implying that SNHG17 not only played an essential role in the malignant progression of PDAC but was also closely associated with TAMs." (PMID 38098044, 2023). "A significantly higher proportion of suppressive B cells (regulatory plasma CD138+ IL10+ and Breg CD20+ IL10+) infiltrate the tumour stroma as opposed to the tumour nest (p<0.0001)." (PMID 37398676, 2023). "The differences in Il-10 and Il-1β expression changes between recombinant CCL21 treatment and upon CCL21 neutralization from GBM CM suggests that CCL21 cooperates with other soluble factors secreted by tumor cells to induce TAM polarization in the TME." (PMID 37314567, 2023). "The activation of TLR4 on macrophages increases the production of IL-10 and C-C Motif Chemokine Ligand 22 (CCL22) that promote the expansion and activation of CD4+CD25highFOXP3+ Tregs, suppressing immune responses against the tumor." (PMID 37345131, 2023).
tumor (continued). "The higher doses of smTRAIL treatment promoted M2-like macrophage recruitment and polarization and increased the production of protumor inflammatory cytokines, such as IL-10, which deepened the suppression of natural killer (NK) cells and CD8+ T cells in the tumor microenvironment." (PMID 37605148, 2023). "Multispectral Spatial analysis of the tumour tissue demonstrated a preponderance of suppressive cell types (CD20+ IL-10+ and CD138+ IL-10+) in the tumour stroma as opposed to the tumour nest." (PMID 37398676, 2023). "We next examined the significance of TGF-β in the pro-tumorigenic effects of macrophages by evaluating the expression of CD163 and interleukin-10 (IL-10) (M2 macrophage markers), as well as matrix metalloprotease 2 (MMP2), which are known to promote tumor progression." (PMID 36980788, 2023). "Secondly, we quantified release of cytokines (i.e., IFNγ, IL-10, IL-2, IL-6, TNFα, GM-CSF, IL-12p70, IL-1b and IL-8) and granzyme B by using the MSD platform in supernatants collected from the TDCC assay with the tumor cell lines SK-CO-1, MKN-45 and H2122 after 48 h." (PMID 38087365, 2023). "Bregs are important immunosuppressive cells in the OC TME; they produce IL-10 and TGFβ, express several immune checkpoints at their surface (PD1, PDL1, OX40 etc) to impair CD4+ and CD8+ T cell proliferation and can promote tumor growth and progression via IL-35 signaling." (PMID 38164130, 2023). "The tumor-bearing mice underwent a therapy combining intratumoral CpG-oligodeoxynucleotides (ODN), a ligand of Toll-like receptor 9 (TLR9), and inhibitory interleukin-10 (IL-10) receptor antibodies (anti-IL-10R)." (PMID 37361202, 2023). "Furthermore, tumour cells can secrete IL‐10, TGF‐β and other cytokines, which inhibit the function of immune cells and facilitate tumour cells to escape from immune attack." (PMID 37921274, 2023). "In addition, active angiogenesis of tumor upregulates the suppressive immune molecules, such as PD-L1, IL-6, IL-10, and Fas ligand, which recruit Tregs into TME and clean up cytotoxic T lymphocytes to make it difficult to kill the tumor cells." (PMID 37345194, 2023). "IM can promote tumor growth in mice by regulating immune responses, such as increasing interferon gamma (IFN-γ)-producing T cells and decreasing interleukin 17a (IL-17a)- and IL-10-producing T cells." (PMID 37009513, 2023). "The AhR has been found to induce the expression of immunoregulatory enzymes and factors such as arginase 1 (Arg1], IDO, IL-10 and the S100 calcium binding protein S100A9 which are important for the immunosuppressive function of TAMCs by creating a tumor-promoting microenvironment." (PMID 37696458, 2023). "Tumor cells may inhibit NK cell function by releasing TGFβ and IL10, although in some cases, IL-10 has also been shown to activate NK cells." (PMID 37274252, 2023). "Additionally, L-SMI induced the accumulation of M2 macrophages, up-regulation immune checkpoint genes and proinflammatory cytokines (IL-6, IL-10, and TGF-β), and alteration the tumor microenvironment and immune status." (PMID 38074647, 2023). "Moreover, IL-10 blockade enhances CAR-T cell activation and cytotoxicity, inducing potent tumor cell death in multiple human tumors." (PMID 37151396, 2023). "However, a different study reported a link between tumor PD-L1 and plasma PD-L1/PD-1 levels and plasma interferon-gamma (IFN-γ) or interleukin-10 (IL-10)." (PMID 38187399, 2023). "An in vitro study showed that B cells suppress tumor immunity by downregulating the expression of IFN-γ in CD8+ T cells, a cytokine possessing antitumor activity, while increasing interleukin-10 (IL-10) production that further inhibits IFN-γ production by T cells." (PMID 37612756, 2023). "In addition, tumour-infiltrating macrophages secrete inflammatory factors and cytokines, such as TGFβ, IL-6, IL-10, and tumour necrosis factor α (TNFα), which promote EMT, have been shown to enrich tumours with CSC-like properties." (PMID 37174052, 2023).
tumor (continued). "Nevertheless, these findings support a vital role of M2 macrophage polarization and a role of IL10 and IL6/STAT3 signaling in HES1 (−) KRAS mutant CRCs that may act in concert to promote tumor progression and metastasis." (PMID 37749297, 2023). "Moreover, upon antigenic activation in vitro, PB CAR-T cells released lower levels of IFN-γ, IL-6, IL-10, TNF-α, CCL2, CXCL10, and GM-CSF than Lenti CAR-T cells, but demonstrated a robust release of IL-9, indicative of a distinct anti-tumor response pathway." (PMID 37228617, 2023). "Notably, B cells can generate different immunosuppressive proteins including IL-10, IL-35 and TGF-β, thus inhibit anti-tumor immunity." (PMID 37936694, 2023). "Tregs play several immunosuppressive roles in the tumor microenvironment, not only inhibiting the function and activation of T cells, APC and NK, but also secreting some immunosuppressive factors such as IL-35, IL-10 and TGF-β." (PMID 37182149, 2023). "For this reason, great efforts are made to reduce the negative effects of tumor-derived IL-10 on the DC properties." (PMID 37033926, 2023). "Manipulated TAMs thus gain secretion of various tumor-promoting factors including CCL18, IL-10, and TGF-β while inhibiting the release of cytotoxic factors like IL-2, IL-12, TNF-α, and IFN-γ, impeding the anti-tumor capacity of other immune components and prolong tumor survival." (PMID 38274812, 2023). "IL-10 production in tumors has been shown to have potential beneficial effects in promoting T cell effector function (i.e. IFN-γ and granzyme production) and limiting tumor growth." (PMID 38054003, 2023). "Moreover, Tregs secrete large amounts of suppressive cytokines such as IL-10 and TGF-β, which further contribute to tumor immune suppression." (PMID 37291128, 2023). "In turn, Treg cells from TME provoke the production of IL-10, TGF-β, and CD73 by TAMs and increase expression of negative co-inhibitory molecules such as PD-L1 in an autocrine way, which later binds to effector T cells and restrains their anti-tumor activity." (PMID 38274812, 2023). "The migration capacity of tumor cells was suppressed, and apoptosis was promoted when tumor cells were cocultured with MPE macrophages in the absence of IL-10." (PMID 37533789, 2023). "The pro-tumor activity of IL-10 relied, at least in part, on the over-expression of SOCS-3 (Suppressor of Cytokine Signaling 3) that in turn inhibited the anti-tumoral IL-6 signaling pathway in macrophages co-cultured with metastatic tumor cells." (PMID 37835437, 2023). "There was no significant change in IL-10 level after the tumor, but the level of IL-10 increased after CTX administration." (PMID 37033618, 2023). "TAMs release anti-inflammatory mediators such as TGF-β1, IL-10 and PGE2, which promote tumor growth, activate angiogenesis, and promote tumor invasion and metastasis through proliferative signaling, regeneration and repair responses, and anti-tumor immune silencing of TAMs." (PMID 37313458, 2023). "IL-10 secretion by both Breg subsets was also increased in tumor-bearing mice treated with Rat IgG, but not in those-treated with GSK, compared to those of naïve mice." (PMID 37291146, 2023). "The CCL4 level did not change in the serum or tumor samples, and the IL-10 level did not change in the samples from the serum." (PMID 37112810, 2023). "Clinical observations and animal studies showed the critical role of C3a in supporting tumor growth: C3 (and C3a cleavage product) produced by CD8 + T cells may promote tumor progression by inhibiting these cells’ IL-10 production." (PMID 37296948, 2023). "Consequently, the delivery system successfully downregulated pro-tumor factors, including IL-10, MMP9, and VEGF, but upregulated anti-tumor factors like IL-12 in TAMs." (PMID 38258072, 2023).
tumor (continued). "The as-synthesized Fe-CDs could selectively induce tumor cells apoptosis by BAX/Caspase 9/Caspase 3/PARP signal pathways and activate antitumoral macrophages by inhibiting the IL-10/Arg-1 axis, contributing to its significant tumor immunotherapy effect." (PMID 37978538, 2023). "IL-8 and IL-10 expression in the malignant CMGTs tissues did not correlate with age, tumor size, tumor metastasis (P > 0.05)." (PMID 36693957, 2023). "Moreover, M2 macrophages secrete vascular endothelial growth factor (VEGF) and potent immunosuppressive cytokines, including IL-10, IL-6, and TGF-β, leading to an enabling environment for tumor proliferation." (PMID 36986856, 2023). "Therefore, macrophage polarization to M2 type can be inhibited by inhibiting this signaling pathway, suppressing the expression of pro-tumor related cytokines such as IL-6, IL-10 and VEGF, and ultimately slowing down tumor disease progression." (PMID 37081874, 2023). "Additionally, the expression levels of M2 markers such as CD206, ARG1, IL-10 and TGF-β were found to be upregulated, ultimately promoting CRC tumor progression and metastasis." (PMID 37943609, 2023). "It has been shown previously that the nonstructural protein of SFTSV can activate the tumor progression locus 2, which promotes the production of IL-10 to suppress the production of IL-6." (PMID 37143532, 2023). "We enrolled two syngeneic murine tumor models (4T1/Balb-c BRCA model and MTCQ1-2/C57BL/6 HNSCC model) to reduce the influence of tumor-type-specific effect and treated the mice with control IgG, IL-10-Fc, αCSF-1R, or BF10." (PMID 37586318, 2023). "Our results showed that all three monocyte subpopulations presented higher expression of IL-10 from patients without MGMT methylation in tumor cells." (PMID 36768201, 2023). "Given the predominance of IL-10, IL-6, IL-1β and VEGF in MDSC secreted supernatant and increased expression of corresponding receptors on tumor cells following co-culture with MDSC and MDSC-supernatant, next we tried to validate the role of individual cytokine in induction of MDR." (PMID 38304256, 2023). "These factors induce the amplification of MDSCs via JAK/STAT, PI3K/Akt, Notch, NF-κB, NLRP3, Wnt and adenosine receptors A2b signaling pathway, and then MDSCs are recruited to the tumor site by PEG-2, resulting in promoting production of iNOS, arginase, IL-10 and TGF-β." (PMID 37064113, 2023). "Conversely, IL-10 was also found to enhance effector function by metabolic reprogramming of terminally exhausted CD8 + T cells and natural killer cells, thereby enhancing anti-tumor immunity." (PMID 37891555, 2023). "Th2 cells always give rise to a humoral immune response that promotes tumor growth through the secretion of IL-10, IL-4, and TGF-β; by contrast, Th1 cells can secrete IFN-γ, TNF-α, and IL-12 to mediate the anti-tumor response and provide successful protection against cancer." (PMID 37345110, 2023). "PD-L1/PD-1 interaction in the tumor microenvironment (TME) also promotes T cell dysfunction, exhaustion, apoptosis, neutralization, and production of Interleukin (IL)-10 creating a state of resistance from Cytotoxic T cell (CD8+) mediated tumor cell destruction." (PMID 36835456, 2023). "Furthermore, lithium tends to induce mature MoDCs to release more IL-10, and IL-5 and transfer CD4+ T cells to the pro-tumor Th2 subtype." (PMID 36831437, 2023). "BMDM or the macrophage cell line Raw264.7 was co-cultured with PY8119 cells to mimic the TNBC microenvironment in vitro, and macrophages were polarized toward pro-tumor M2 phenotype and M2 markers Arg-1, CD206, Fizz-1, Ym1 and IL-10 were upregulated significantly." (PMID 37925462, 2023). "Consequently, this led to upregulation of immunosuppressive cytokines (IL-10), as well as genes involved in the recruitment of MDSC and tumor cell extravasation, rendering the premetastatic niche more attractive for tumor cell colonization." (PMID 38087370, 2023).